Y_RNA (Y RNA )
Gene: Miscellaneous RNA gene on chromosome 14 (90,177,222 to 90,177,330, forward strand). Ensembl gene ENSG00000201351.
Homologues: Orthologues: chimpanzee Y_RNA (100% identical), macaque Y_RNA (93% identical), mouse Gm56393 (74% identical). Paralogues in human: RNY1 (92% identical), Y_RNA (90% identical), Y_RNA (88% identical), RNY1P2 (87% identical), Y_RNA (87% identical), Y_RNA (86% identical), Y_RNA (85% identical), RNY1P11 (84% identical), Y_RNA (84% identical), Y_RNA (83% identical), RNY1P12 (83% identical), RNY1P8 (83% identical), and 96 more.